HNF1A (HNF1 homeobox A)
Diseases named in the same sentence as HNF1A in open-access papers (continued):
Sharing a sentence is not in itself a finding about the gene and the disease.
diabetes (continued). "Exome sequencing in diabetes presents a diagnostic challenge because depending on frequency, functional impact, and genomic and environmental contexts, HNF1A variants can cause maturity-onset diabetes of the young (MODY), increase type 2 diabetes risk, or be benign." (PMID 32910913, 2020). "HNF1A activity dysfunction causes a reduction β-cell mass and induces onset of diabetes." (PMID 31109344, 2019). "The diabetes-related HNF1A p.I27L gene was associated with insulin resistance, which might contribute to developing GDM." (PMID 31114636, 2019). "As the clinical phenotype of HNF1A-MODY diabetes varies considerably, we used human induced pluripotent stem cells (hiPSCs) from two healthy individuals (control) to generate isogenic lines with mutation in HNF1A gene." (PMID 31739614, 2019). "Subjects with diabetes and a rare HNF1A allelic variant were predominantly females (P = 0.02)." (PMID 29666556, 2018). "HNF1A variants can cause diabetes and might be involved in the development of primary liver neoplasm." (PMID 30155490, 2018). "In this study, we compared the levels of serum miR-122 among Chinese patients with different forms of diabetes, including HNF1A-DM, T2DM, type 1 diabetes (T1DM), glucokinase variant-induced diabetes (GCK-DM), and mitochondrial A3243G mutation-induced diabetes (MDM)." (PMID 30155490, 2018). "Prompt transfer to sulfonylureas, enabling optimal glycaemic control soon after diabetes diagnosis, may reduce the risk of future complications in those with HNF1A/HNF4A-MODY, as seen with type 1 and type 2 diabetes." (PMID 30229274, 2018). "In humans, mutations in HNF-1α gene cause MODY3 (Maturity Onset Diabetes of Young)." (PMID 28854935, 2017). "Moreover, when overlaying with other canonical pathways in NASH, HNF4A and HNF1A are linked with to hepatic cholestasis, diabetes and FXR/RXR activation." (PMID 29216278, 2017). "Furthermore, T2D genetic risk plays a small role in LADA, with a degree of evidence for the HNF1A locus, highlighting the potential for genetic risk scores to contribute towards defining diabetes subtypes." (PMID 28438156, 2017). "The differences in the gut microbiota between patients with T2DM and HNF1A-MODY in relation to healthy individuals could be a new argument for an influence of microbiota as an environmental risk factor for some forms of diabetes." (PMID 27807544, 2016). "Functional analysis demonstrated that the HNF4A gene mutation T130I causes reduced expression in HeLa cells and thus affects protein function, whereas the HNF1A polymorphisms p.I27L and p.S487N may be associated with the age of diagnosis of diabetes." (PMID 26981542, 2016). "These efforts could shed a novel light for better understanding of the mechanism that leads to diabetes caused by Hnf1a-deficiency." (PMID 27667715, 2016). "Here, we identified the p.I27L and p.S487N polymorphisms in HNF1A in a diabetes family." (PMID 26981542, 2016). "Diabetes caused by HNF1A and HNF4A mutations is classically responsive to sulphonylurea treatment." (PMID 27330718, 2016). "Consequently, markedly lower high sensitivity CRP (hsCRP) levels are seen in monogenic diabetes as a result of an HNF1A mutation than in other forms of diabetes." (PMID 23766565, 2013). "Mutations in HNF1A are the most commonly encountered form of monogenic diabetes with a minimum prevalence of 50–60 cases per million population (accounting for 52% of all cases of monogenic diabetes) or 1-2% of all patients with diabetes." (PMID 23766565, 2013). "Thus, some patients harboring the HNF1A mutation develop liver disease before the onset of diabetes." (PMID 22672869, 2012). "She later developed diabetes, and germline mutation of the HNF1A gene was subsequently identified." (PMID 22672869, 2012). "Interestingly, in individuals with monogenic diabetes due to known, severe mutations in the HNF-1α gene, a significantly reduced age at diagnosis is also associated with exposure to diabetes in utero." (PMID 22288007, 2012).
diabetes (continued). "Furthermore, cosegregation of liver adenomatosis and diabetes in 4 families and 1 patient harboring germline HNF1A mutations has been described." (PMID 22672869, 2012). "However, HNF1A G319S carriers who were active smokers had increased risk of developing diabetes in the present study." (PMID 21208426, 2011). "Furthermore, cigarette smoking appears to amplify incident diabetes risk in carriers of HNF1A G319S." (PMID 21208426, 2011). "When participants were stratified by baseline smoking status, HNF1A G319S carriers who were active smokers had increased risk of developing diabetes (OR 6.91 [95% CI 3.38-14.12]), while the association was attenuated to non-significance among non-smokers (1.11 [0.40-3.08])." (PMID 21208426, 2011). "We aimed to investigate whether CRP was mediating the association between HNF1A G319S and type 2 diabetes in an Aboriginal Canadian population with a high prevalence of diabetes." (PMID 20716378, 2010). "HNF1A is a frequent cause of monogenic diabetes, albeit with early-onset." (PMID 19490620, 2009). "The increased cardiovascular risk associated with HNF1A-diabetes provides another reason that carefully designed larger, long-term comparison studies of glycemic and cardiovascular outcomes of these newer classes of diabetes medications, which offer cardiovascular benefit, are needed." (PMID 39025920, 2024). "Additionally, four of the ten monogenic diabetes genes (HNF1A, GCK, ABCC8 and INS) exhibited P < 0.05 rare variant associations with youth-onset T2D in our primary gene-level analysis (which included both pathogenic and likely pathogenic and additional variants)." (PMID 38278947, 2024). "rs1169288 and other SNPs in the HNF1A gene have been previously associated with susceptibility to T2D and gestational diabetes, while, to our knowledge, no studies have already reported an association of rs1169286 with any polygenic form of diabetes, including T1D." (PMID 37509590, 2023). "Moreover, smoking appears to increase the risk of diabetes in HNF1α G319S carriers." (PMID 35299962, 2022). "In conclusion, the etiology of diabetes in patient D16 may be caused by the dominant negative effect of the HNF1A Q141Hfs*47 mutant polypeptide, consequently affecting the expression level of many HNF1A‐dependent genes involved in glucose metabolism and the normal beta cell function." (PMID 28116330, 2017). "Although some patients with monogenic diabetes caused by HNF1A or GCK mutations may show poor metabolic control, this is usually due to comorbidity with type 1 or type 2 diabetes, making it impossible to study the impact of high HbA1c in “pure” monogenic diabetes." (PMID 24549415, 2014). "Finally, the example of single gene diabetes, particularly HNF1A MODY and permanent neonatal diabetes associated with the KCNJ11 and ABCC8 genes, all efficiently controlled on sulfonylurea, inspires us to continue the efforts to tailor individual treatment for T2DM patients." (PMID 22996131, 2012). "Humans with mutations in the genes encoding for the transcription factors Hnf1α and Hnf4α develop similar forms of diabetes that result from abnormal insulin secretion, suggesting that the two factors might have related functions in insulin-producing islet-cells." (PMID 20523905, 2010). "Therefore, the authors argued that variation in genes including HNF1A may have subsequent impact on vascular disease and diabetes risk that is influenced or marked by circulating CRP concentrations." (PMID 20716378, 2010). "HNF1A might therefore have an impact on vascular disease and diabetes risk that is mediated by CRP." (PMID 20716378, 2010). "A heterozygous HNF1A(NM_000545.8):ex1_10del was suspected by next-generation sequencing (NGS) using a hereditary diabetes gene panel.This finding was validated using multiplex ligation-dependent probe amplification (MLPA)." (PMID 41778156, 2026). "Time from the diagnosis of diabetes was longer in subtypes HNF1A-MD (8.00 ± 6.20 vs. 3.46 ± 4.05 years, p=0.046)." (PMID 41409604, 2025).
diabetes (continued). "Most types of monogenic diabetes have reduced penetrance and variable expressivity, including HNF1A, HNF4A, and RFX6, which is considered a candidate gene for MODY, emphasizing the role of environment and genetic factors." (PMID 40148250, 2025). "Patients 1 (with an HNF1A gene mutation, MODY3) and 5 (with an-INS gene mutation, MODY10) were initially diagnosed with type 1 diabetes mellitus (T1D) due to the immediate requirement for insulin therapy at diagnosis." (PMID 41020216, 2025). "Variants in the genes GCK, HNF1A, HNF1B, HNF4A, ABCC8, INS, and INSR were the main contributors to the genetic pathogenesis of hereditary diabetes mellitus in the Russian cohort." (PMID 39859454, 2025). "The ClinGen Monogenic Diabetes Variant Curation Expert Panel (MDEP) was established in 2017 and has developed and published gene-specific rules for HNF1A, HNF4A, GCK, and monogenic diabetes, with others in progress." (PMID 41516031, 2025). "Thirdly, we only incorporated 20 patients with monogenic diabetes, which is difficult to highlight the effect of mutations in HNF1β, HNF4A, and HNF1A genes associated with Lp(a) expression on Lp(a) concentration in patients with early-onset T2DM." (PMID 40370778, 2025). "HNF1A diabetes is the most common type of MODY requiring treatment and the prevalent form in northern Europe." (PMID 39903441, 2025). "Two randomized, double-blinded cross-over studies compared alternative and augmentative regimens to SU monotherapy in HNF1A-diabetes." (PMID 39025920, 2024). "What is the optimal glucose-lowering therapy in the three commonest subtypes of autosomal dominant familial diabetes (MODY): GCK-related hyperglycemia, HNF1A-diabetes, and HNF4A-diabetes?" (PMID 39025920, 2024). "Phenotypic features of young onset of diabetes in a lean individual with predominant postprandial dysglycaemia overlaps with HNF1A-MODY." (PMID 38933924, 2024). "MODY 3 is caused by mutations in the hepatocyte nuclear factor 1A (HNF1A) and constitutes a rare type of monogenic diabetes, all forms of MODY accounting for 1–2% of diabetes cases in adulthood." (PMID 38311659, 2024). "The strongest evidence in this systematic review for precision therapy was for the use of SU in HNF1A-diabetes." (PMID 39025920, 2024). "Our data provides a valuable resource to investigate the downstream targets of HNF4A and HNF1A, to identify molecular mechanisms in normal beta cells and hepatic cells as well as their dysfunction in the context of diabetes." (PMID 38909044, 2024). "We analyzed studies for evidence of SU as an effective glucose-lowering therapy for HNF1A-diabetes and HNF4A-diabetes." (PMID 39025920, 2024). "Limited evidence from the mostly non-randomized, small studies supports no treatment in glucokinase-related hyperglycemia and sulfonylureas for HNF1A-diabetes; further evidence is needed on the optimum treatments in these and other monogenic subtypes." (PMID 39025920, 2024). "A previous investigation presented genetic proof that mutations in PCBD1 can lead to the development of early-onset nonautoimmune diabetes, which exhibits characteristics resembling dominantly inherited HNF1A-diabetes." (PMID 38660376, 2024). "Heterozygous inactivating mutations in HNF1A and HNF4A genes can have a bi-phasic presentation, with transient or prolonged HH in infancy and diabetes in adolescence or young adulthood." (PMID 39421536, 2024). "In another study, patients diagnosed with early type 2 diabetes were examined for mutations in the HNF1A, HNF4A, and GCK genes; a monogenetic form of diabetes was diagnosed in 4%." (PMID 38550917, 2024). "Although in Europe HNF4A-MODY, GCK-MODY, and HNF1A-MODY, carry the most common pathogenic variants, accounting for > 80% of all monogenic diabetes, in the MENA region, MODY prevalence is mainly unexplored." (PMID 39191897, 2024). "Diabetes exposure in utero results in an earlier age at diagnosis of diabetes in heterozygous HNF1A offspring (15.5 ± 5.4 vs. 27.5 ± 13.1 years, p = 0.05)." (PMID 38933924, 2024).
diabetes (continued). "A randomized trial (18 individuals per group) shows that sulfonylureas (SU) were more effective in HNF1A-diabetes than in type 2 diabetes." (PMID 39025920, 2024). "While there is some support for no treatment in GCK-related hyperglycemia and sulphonylureas for HNF1A-diabetes, overall there is limited evidence to guide the treatment in monogenic diabetes with most studies being non-randomized and small." (PMID 39025920, 2024). "The study compared the fasting plasma glucose (FPG) response in individuals with HNF1A-diabetes (N = 18) and type 2 diabetes (N = 18) to therapy with SU (gliclazide) or metformin for 6 weeks." (PMID 39025920, 2024). "What is the optimal glucose-lowering therapy in the three commonest subtypes of autosomal dominant familial diabetes also known as Maturity Onset Diabetes of the Young (MODY): GCK-related hyperglycemia, HNF1A-diabetes, and HNF4A-diabetes?" (PMID 39025920, 2024). "Patients with HNF1A-diabetes exhibit reduced insulin secretory capacity, while those with GCK-diabetes display defective glucose sensitivity but retain insulin secretory capacity." (PMID 39902162, 2024). "Further studies are needed to elucidate factors that influence the response to SU within HNF1A-diabetes." (PMID 39025920, 2024). "Firth logistic regression models were developed on data from 3541 paediatric patients from the Swedish ‘Better Diabetes Diagnosis’ (BDD) population study (n = 46 (1.3%) MODY (HNF1A, HNF4A, GCK))." (PMID 38719926, 2024). "Our findings are consistent with other countries’ data that GCK and HNF1A are the most common forms of monogenic diabetes." (PMID 37033247, 2023). "This comprehensive approach can be used to systematically screen and identify HNF1A-MODY and certain other MODY types, and lead to increased diagnostic precision in children with diabetes." (PMID 37798422, 2023). "Future studies are needed to validate the contribution of the HNF1A/FXYD2 pathway to diabetes and to explore options to manipulate β-cell heterogeneity for clinical uses." (PMID 37669939, 2023). "Where NGS was employed, the monogenic diabetes diagnostic yield increased by around 30% compared to Sanger sequencing of GCK, HNF1A and HNF4A alone, and resulted in the (often unexpected) diagnosis of rare syndromic forms of diabetes, most commonly m.3243A>G." (PMID 37794142, 2023). "HNF1A haploinsufficiency underlies the most common form of human monogenic diabetes (HNF1A–maturity onset diabetes of the young [HNF1A-MODY]), and hypomorphic HNF1A variants confer type 2 diabetes risk." (PMID 37943614, 2023). "For monogenic diabetes in clinically unselected cohorts, pathogenic variants in GCK display near-complete penetrance, while variants in HNF1A and HNF4A show reduced penetrance." (PMID 37285546, 2023). "Individuals with HNF1A MODY are likely to develop extra pancreatic symptoms such as glycosuria which will appear even before the onset of diabetes due to a low renal glucose threshold." (PMID 37396188, 2023). "This article aims to characterize the differences in results from routine examinations between GCK‐MODY and hepatocyte nuclear factor 1‐α (HNF1A)‐MODY or type 2 diabetes (T2D) patients in different periods of diabetes." (PMID 37226652, 2023). "When we considered probands of Group 1 with a parental history of hyperglycemia, 58.3% (21/36) had a positive genetic test for GCK or HNF1A genes, while pick-up rate was 18.1% (4/22) in patients with mute family history for diabetes." (PMID 36178555, 2023). "The HNF1A gene was also involved in the development of multifactorial forms of diabetes, probably affecting beta cell function." (PMID 37509590, 2023). "Based on this robust classification, we estimate that the prevalence of HNF1A-MODY is 0.3% in paediatric diabetes." (PMID 37798422, 2023). "Notable downregulated TFs include HNF1A/B and RFX6, which have known diabetes association and/or play important roles in β-cell function." (PMID 37669939, 2023).
diabetes (continued). "HNF1A-MODY (Maturity Onset Diabetes of the Young type 3) is one of the most common subtypes of MODY." (PMID 37396173, 2023). "Two in the ICAlow group had pathogenic variants in HNF1A and GCK, resulting in a monogenic diabetes prevalence of 4.1% (2/49)." (PMID 36418577, 2023). "The benign trajectory of diabetes due to pathogenic GCK mutations, and the sulfonylurea-hyperresponsiveness conferred by activating KCNJ11 or ABCC8 mutations, or loss-of-function HNF1A or HNF4A mutations, often decisively guide clinical management." (PMID 35618782, 2022). "In this genome-wide association study, we identified several variants with suggestive evidence for a modulatory effect on age of diabetes onset in a group of 843 HNF1A-MODY patients." (PMID 36104811, 2022). "The genetic background of family A associated with metabolic abnormalities increased insulin resistance in the HNF1α p.Ala180Val carriers, leading to marked diabetes." (PMID 35299962, 2022). "A lower BMI coupled with the decrease of insulin secretion before the onset of diabetes is the pre-diabetic physiologic state of individuals with HNF1A-T2D." (PMID 35299962, 2022). "In a Cox model, +1 SD of T2D-PRS increased the risk of diabetes by 28%, whereas in a linear regression model +1 SD of T2D-PRS was associated with a 3 year earlier diagnosis of HNF1A-diabetes." (PMID 34951657, 2022). "Pathogenic variants in HNF1A and HNF4A cause progressive beta-cell dysfunction leading to diabetes whereas pathogenic variants in GCK cause stable mild hyperglycemia." (PMID 36257325, 2022). "Sequencing of large populations has indeed identified some rare variants (e.g. in MTNR1B, PPARG, SLC30A8, HNF1A, PDX1, PAM) that confer risk of type 2 diabetes that is intermediate between common SNPs and mutations causing monogenic diabetes." (PMID 35618782, 2022). "The cohort study confirmed the excellent performance of α1-3,4 fucosylation levels as a clinical biomarker for HNF1A-MODY, which allows identification and classification of cases with diabetes carrying damaging variants in the HNF1A gene." (PMID 34939081, 2022). "Similar to humans, HNF1A-null mice exhibit abnormal glucose-stimulated insulin secretion and develop diabetes two weeks after birth, expressing low levels of insulin and insulin-like growth-factor-1 (Igf1)." (PMID 36361703, 2022). "Similar to HNF1A, for individuals with a HNF4A pathogenic variants, the age-related penetrance of diabetes was lower in the family members, the Geisinger cohort and the UK Biobank compared to MODY probands (log rank test, all p < 8 × 10−11)." (PMID 36257325, 2022). "We comprehensively assess the penetrance and prevalence of pathogenic variants in HNF1A, HNF4A, and GCK that account for >80% of monogenic diabetes." (PMID 36257325, 2022). "Maturity-onset of diabetes of the young is associated with defects in 14 different genes, the most common ones being GCK, HNF4A, HNF1A, and HNF1B." (PMID 35640144, 2022). "The m.3243A>G mutation is the 4th most common cause of monogenic diabetes (8% of all monogenic cases) after mutations in GCK, HNF1A and HNF4A in patients with suspected MODY." (PMID 34789499, 2022). "Increased complexity of plasma N-glycans is also associated with other neuropsychiatric disorders, as well as diabetes, HNF1A-MODY and other autoimmune and inflammation-related states." (PMID 35741825, 2022). "Pathogenic variants in HNF1A and HNF4A show the highest risk of diabetes in clinically selected individuals but had substantially lower risk in clinically unselected settings." (PMID 36257325, 2022). "In a larger subsequent series, 70% of the participants with HNF1A-MODY were diagnosed with diabetes by the age of 25 and 85% by 35 years." (PMID 34951657, 2022). "Pathogenic variants in HNF1A (MIM: 142410), HNF4A (MIM: 600281), and GCK (MIM: 138079) account for >80% of all monogenic diabetes." (PMID 36257325, 2022).